ANGEL2 (angel homolog 2)
Description:
RNA 2',3'-cyclic phosphatase that catalyzes the hydrolysis of RNA molecules with a 2',3'-cyclic phosphate at the 3' end to produce RNA with a linear 3'-phosphate group. Essential for the maturation and processing of mitochondrial RNAs, particularly those generated via non-canonical pathways (By similarity). Antagonizes pre-tRNA processing and XBP1 mRNA splicing during the unfolded protein response by limiting the availability of 2',3'-cyclic phosphate substrates for the tRNA ligase complex. Promotes tRNA recycling by eliminating 2',3'-cyclic phosphate groups from cleaved tRNAs, thereby enabling the tRNA nucleotidyltransferase TRNT1 to reattach the CCA tail essential for aminoacylation and subsequent translation.
Synonyms: KIAA0759L; FLJ12793; Ccr4d
Tractability: Small molecule: a structure with a bound ligand is known. PROTAC: ubiquitination databases record sites on it; its protein half-life has been measured.
Gene: Protein-coding gene on chromosome 1 (212,992,182 to 213,015,867, reverse strand). Ensembl gene ENSG00000174606.
Subcellular location: Mitochondrion matrix
Subcellular location (Human Protein Atlas): Nucleoplasm; Mitochondria; Nuclear bodies
Gene Ontology:
Molecular function: magnesium ion binding; mRNA 3'-UTR binding; RNA 2',3'-cyclic phosphatase activity; RNA 2'-phosphatase activity; catalytic activity
Biological process: 3'-UTR-mediated mRNA stabilization; negative regulation of mitotic cell cycle; negative regulation of RNA splicing; negative regulation of tRNA processing; nuclear-transcribed mRNA catabolic process, non-stop decay; mitochondrial mRNA 3'-end processing
Cellular component: Cajal body; cytoplasm; mitochondrial matrix; mitochondrion; nucleus
Genetic constraint (gnomAD): Loss-of-function variants: 41 observed, 67.53 expected, observed/expected ratio (o/e) 0.61, 90% interval 0.47 to 0.79. The upper end of that interval is the gene's LOEUF score, 0.79, which puts it in group 3 of 6, group 1 being the genes least tolerant of losing a copy. Missense variants: 561 observed, 672.68 expected, observed/expected ratio (o/e) 0.83, 90% interval 0.78 to 0.89. Synonymous variants: 208 observed, 240.44 expected, observed/expected ratio (o/e) 0.87, 90% interval 0.77 to 0.97.
Homologues: Orthologues: chimpanzee ANGEL2 (100% identical), macaque ANGEL2 (99% identical), dog ANGEL2 (94% identical), pig ANGEL2 (92% identical), guinea pig ANGEL2 (90% identical), rat Angel2 (87% identical), mouse Angel2 (85% identical), rabbit ANGEL2 (65% identical), tropical clawed frog angel2 (54% identical), zebrafish angel2 (48% identical), Drosophila melanogaster angel (21% identical), Caenorhabditis elegans angl-1 (21% identical). Paralogues in human: ANGEL1 (37% identical), CNOT6 (19% identical), CNOT6L (19% identical), PDE12 (19% identical), NOCT (18% identical).
Diseases named in the same sentence as ANGEL2 in open-access papers:
ANGEL2 is named in the same sentence as 3 diseases in open-access papers, as found by Europe PMC text mining. Sharing a sentence is not in itself a finding about the gene and the disease. The quoted sentences say what the papers report.
meningioma (1 paper, 2023). A generally slow growing tumor attached to the dura mater. "Investigation of antigen distribution across all WHO grades yielded six common meningioma-associated antigens (A4GALT, FBN2, SNED1, MPP6, PCED1B, and ANGEL2)." (PMID 37368072, 2023).
metastatic disease (1 paper, 2016). "The integrated genetics and gene expression analysis that initially identified Cnot2 also implicated other genes associated with RNA deadenylation (Cnot8, Angel2, Tob1) as potential modulators of metastatic disease, suggesting that this function of CCR4-NOT might be a critical determinant." (PMID 26807845, 2016).
cancer (1 paper, 2021). A tumor composed of atypical neoplastic, often pleomorphic cells that invade other tissues. "The three prognostic markers (PAPSS2, ANGEL2, and MPP1) that hyper‐hydroxymethylated in CIN3 also play important roles in cancers." (PMID 34323415, 2021).